INSR (insulin receptor)
Description:
Receptor tyrosine kinase which mediates the pleiotropic actions of insulin. Binding of insulin leads to phosphorylation of several intracellular substrates, including, insulin receptor substrates (IRS1, 2, 3, 4), SHC, GAB1, CBL and other signaling intermediates. Each of these phosphorylated proteins serve as docking proteins for other signaling proteins that contain Src-homology-2 domains (SH2 domain) that specifically recognize different phosphotyrosine residues, including the p85 regulatory subunit of PI3K and SHP2. Phosphorylation of IRSs proteins lead to the activation of two main signaling pathways: the PI3K-AKT/PKB pathway, which is responsible for most of the metabolic actions of insulin, and the Ras-MAPK pathway, which regulates expression of some genes and cooperates with the PI3K pathway to control cell growth and differentiation. Binding of the SH2 domains of PI3K to phosphotyrosines on IRS1 leads to the activation of PI3K and the generation of phosphatidylinositol-(3, 4, 5)-triphosphate (PIP3), a lipid second messenger, which activates several PIP3-dependent serine/threonine kinases, such as PDPK1 and subsequently AKT/PKB. The net effect of this pathway is to produce a translocation of the glucose transporter SLC2A4/GLUT4 from cytoplasmic vesicles to the cell membrane to facilitate glucose transport. Moreover, upon insulin stimulation, activated AKT/PKB is responsible for: anti-apoptotic effect of insulin by inducing phosphorylation of BAD; regulates the expression of gluconeogenic and lipogenic enzymes by controlling the activity of the winged helix or forkhead (FOX) class of transcription factors. Another pathway regulated by PI3K-AKT/PKB activation is mTORC1 signaling pathway which regulates cell growth and metabolism and integrates signals from insulin. AKT mediates insulin-stimulated protein synthesis by phosphorylating TSC2 thereby activating mTORC1 pathway. The Ras/RAF/MAP2K/MAPK pathway is mainly involved in mediating cell growth, survival and cellular differentiation of insulin. Phosphorylated IRS1 recruits GRB2/SOS complex, which triggers the activation of the Ras/RAF/MAP2K/MAPK pathway. In addition to binding insulin, the insulin receptor can bind insulin-like growth factors (IGFI and IGFII). Isoform Short has a higher affinity for IGFII binding. When present in a hybrid receptor with IGF1R, binds IGF1. PubMed:12138094 shows that hybrid receptors composed of IGF1R and INSR isoform Long are activated with a high affinity by IGF1, with low affinity by IGF2 and not significantly activated by insulin, and that hybrid receptors composed of IGF1R and INSR isoform Short are activated by IGF1, IGF2 and insulin. In contrast, PubMed:16831875 shows that hybrid receptors composed of IGF1R and INSR isoform Long and hybrid receptors composed of IGF1R and INSR isoform Short have similar binding characteristics, both bind IGF1 and have a low affinity for insulin. In adipocytes, inhibits lipolysis (By similarity).
Synonyms: CD220; HHF5
Tractability: Small molecule: a drug acting on it is in phase 2 or 3 trials; a structure with a bound ligand is known; a high-quality ligand is known; it has a high-quality binding pocket; it belongs to a druggable protein family. Antibody: its Gene Ontology location is reachable by antibodies, with high confidence; UniProt places it where antibodies can reach, with medium confidence; UniProt predicts a signal peptide or a membrane-spanning region; the Human Protein Atlas places it where antibodies can reach. PROTAC: UniProt records ubiquitination sites on it; ubiquitination databases record sites on it; its protein half-life has been measured; a small molecule that binds it is known. Other modalities: an approved drug acts on it.
Target class: Enzyme; Tyrosine protein kinase InsR family; TK protein kinase group; Kinase; Protein Kinase
Chemical probes: linsitinib (high quality)
Safety:
Unwanted effects reported when the protein is acted on. In parentheses: how it was acted on, where the effect was seen, and who reports it.
anxiety (inhibition; central nervous system; source: Brennan et al. (2024))
Carcinogenicity (activation; source: Brennan et al. (2024))
cardiac hypertrophy (inhibition; cardiovascular; source: Brennan et al. (2024))
Hyperglycaemia (inhibition; metabolic/endocrine; source: Brennan et al. (2024))
hyperlipidaemia (inhibition; source: Brennan et al. (2024))
neoplasm/ malignancy (activation; source: Brennan et al. (2024))
neutropenia (source: ClinPGx)
Gene: Protein-coding gene on chromosome 19 (7,112,255 to 7,294,414, reverse strand). Ensembl gene ENSG00000171105.
Subcellular location: Cell membrane; Late endosome; Lysosome
Subcellular location (Human Protein Atlas): Plasma membrane; Vesicles; Basal body; Centriolar satellite; Primary cilium transition zone
Pathways (Reactome):
Signal Transduction: IRS activation; Insulin receptor recycling; Insulin receptor signalling cascade; PI5P, PP2A and IER3 Regulate PI3K/AKT Signaling; Signal attenuation; Signaling by Insulin receptor
Gene Ontology:
Molecular function: amyloid-beta binding; ATP binding; GTP binding; insulin binding; insulin receptor activity; insulin receptor substrate binding; insulin-like growth factor I binding; insulin-like growth factor II binding; insulin-like growth factor receptor binding; phosphatidylinositol 3-kinase binding; protein binding; protein domain specific binding; protein kinase activator activity; protein tyrosine kinase activity; protein-containing complex binding; PTB domain binding; cargo receptor activity; protein kinase activity; transmembrane receptor protein tyrosine kinase activity
Biological process: cellular response to insulin stimulus; G protein-coupled receptor signaling pathway; glucose homeostasis; heart morphogenesis; insulin receptor signaling pathway; positive regulation of canonical NF-kappaB signal transduction; positive regulation of cell migration; positive regulation of cell population proliferation; positive regulation of D-glucose import; positive regulation of developmental growth; positive regulation of glycogen biosynthetic process; positive regulation of glycolytic process; positive regulation of MAPK cascade; positive regulation of mitotic nuclear division; positive regulation of nitric oxide biosynthetic process; positive regulation of phosphatidylinositol 3-kinase/protein kinase B signal transduction; positive regulation of receptor internalization; positive regulation of respiratory burst; protein autophosphorylation; regulation of DNA-templated transcription; regulation of embryonic development; symbiont entry into host cell; amyloid-beta clearance; dendritic spine maintenance; learning; and 18 more
Cellular component: caveola; extracellular exosome; insulin receptor complex; membrane; nuclear envelope; nuclear lumen; plasma membrane; receptor complex; axon; dendrite membrane; endosome membrane; external side of plasma membrane; late endosome; lysosome; neuronal cell body membrane
Genetic constraint (gnomAD): Loss-of-function variants: 65 observed, 143.6 expected, observed/expected ratio (o/e) 0.45, 90% interval 0.37 to 0.56. The upper end of that interval is the gene's LOEUF score, 0.56, which puts it in group 2 of 6, group 1 being the genes least tolerant of losing a copy. Missense variants: 1,216 observed, 1,862.9 expected, observed/expected ratio (o/e) 0.65, 90% interval 0.62 to 0.68. Synonymous variants: 730 observed, 750.92 expected, observed/expected ratio (o/e) 0.97, 90% interval 0.91 to 1.03.
Gene-disease validity (ClinGen):
ClinGen rates the evidence that INSR causes each of these diseases.
Donohue syndrome (autosomal recessive): Definitive. Leprechaunism is a congenital form of extreme insulin resistance (a group of syndromes that also includes Rabson-Mensenhall syndrome, type A insulin-resistance syndrome, and acquired type B insulin-resistance syndrome) characterized by intrauterine and mainly postnatal severe growth retardation.
Homologues: Orthologues: chimpanzee INSR (98% identical), dog INSR (97% identical), pig INSR (96% identical), rat Insr (95% identical), rabbit INSR (95% identical), mouse Insr (95% identical), guinea pig INSR (94% identical), macaque INSR (91% identical), tropical clawed frog insr (70% identical), zebrafish insra (68% identical), zebrafish insrb (65% identical). Paralogues in human: IGF1R (57% identical), INSRR (50% identical), ROS1 (18% identical), MET (16% identical), ALK (16% identical), NTRK3 (15% identical), EPHA3 (15% identical), EPHB1 (15% identical), ERBB2 (15% identical), EPHA5 (15% identical), NTRK2 (14% identical), EPHA7 (14% identical), and 41 more.
Diseases named in the same sentence as INSR in open-access papers:
INSR is named in the same sentence as 397 diseases in open-access papers, as found by Europe PMC text mining. Sharing a sentence is not in itself a finding about the gene and the disease. The quoted sentences say what the papers report.
Insulin resistance (1,469 papers, 2002 to 2026). Increased resistance towards insulin, that is, diminished effectiveness of insulin in reducing blood glucose levels. "Ganglioside GM3 accumulated in GD negatively affects the insulin receptor in the membrane lipid structure, reduces insulin sensitivity, and causes insulin resistance." (PMID 41507929, 2026). "Exposure to pesticides led to body weight gain and insulin resistance in wild-type and M83 mice, caused, at least in part, by a reduction in insulin receptor levels in liver, skeletal muscle and adipose tissue." (PMID 42203108, 2026). "Mutations in the INSR gene result in metabolic disorders, and the decrease in both INSR and its post-receptor components is strongly associated with insulin resistance." (PMID 39747658, 2025). "A current study on mice also supported this association; homocysteine inhibited pro-insulin receptor cleavage and caused insulin resistance via protein cysteine-homocysteinylation." (PMID 40364032, 2025). "ROS cause insulin resistance in peripheral tissues by affecting insulin receptor signaling pathways." (PMID 40729004, 2025). "High autoantibody levels inhibit the INSR (antagonistic role), causing insulin resistance and hyperglycemia, while low levels of these autoantibodies partially agonize insulin-mimetic activity, causing hypoglycemia." (PMID 40565151, 2025). "Rare syndromes, like Donohue and Rabson–Mendenhall syndromes, caused by mutations in the insulin receptor (INSR) gene or autoantibodies against the receptor, confirm that defects in proximal signaling can induce insulin resistance." (PMID 40806697, 2025). "Mechanistically, mutations in the insulin receptor led to insulin resistance in these cave‐dwelling specimens." (PMID 41383212, 2025). "For instance, excessive lipid accumulation increases ceramide and DAG levels in obesity and type-2 diabetes, affecting insulin receptor signaling and causing insulin resistance." (PMID 41373990, 2025). "Reduced intracellular Mg2+ can impair insulin receptor (IR) activity, damage post-receptor effects, and increase insulin resistance, all of which are risk factors for GDM." (PMID 41235310, 2025). "ROS cause insulin resistance in the peripheral tissues by affecting various points in insulin receptor signal transduction, ultimately resulting in decreased GLUT4 translocation and expression of the GLUT4 transporter in the cellular membrane." (PMID 41473239, 2025). "These inflammatory factors can inhibit the phosphorylation of insulin receptor substrate, disrupt the insulin signalling pathway, and cause insulin resistance." (PMID 40878475, 2025). "Donohue syndrome (DS) is a rare autosomal recessive disorder caused by homozygous or compound heterozygous mutations in insulin receptor (INSR), leading to severe insulin resistance." (PMID 41025026, 2025). "Insulin resistance is associated with an impaired insulin signaling pathway, caused by defects in function of the insulin receptor." (PMID 39859258, 2025). "Insulin resistance plays a significant role in muscle atrophy in diabetes mellitus, causing abnormal insulin signaling by reducing tyrosine phosphorylation of the insulin receptor and phosphorylation of Akt." (PMID 38916919, 2025). "Severe insulin resistance is typically caused by mutations in the INSR gene, located on chromosome 19p13.2, which consists of 22 exons and 21 introns." (PMID 40309171, 2025). "Insulin resistance is associated with impaired GLUT4 translocation due to disrupted tyrosine phosphorylation of insulin receptor substrates (IRS)." (PMID 41256917, 2025). "Ceramides are linked to insulin resistance, inflammation, and endothelial dysfunction by disrupting insulin receptor signaling and promoting mitochondrial reactive oxygen species." (PMID 40548377, 2025).
Insulin resistance (continued). "It has been observed that MA can reduce the phosphorylation of protein kinase B, alter the expression of the insulin receptor, decrease urinary citrate secretion, increase magnesium excretion, and eventually cause insulin resistance." (PMID 40510502, 2025). "Our group has clarified the effect of insulin resistance on AD pathology using AD model mice harboring the P1195L mutation in the insulin receptor, which diminishes the receptor tyrosine kinase activity to induce insulin resistance." (PMID 40443027, 2025). "Caveolin-1 is essential for improving insulin sensitivity, and studies have shown that Cav-1-deficient mice exhibit insulin resistance and defective insulin receptor protein expression." (PMID 41280311, 2025). "Loss of insulin signaling due to the selective deletion of the insulin receptor in hepatocytes leads to glucose intolerance associated with severe insulin resistance and strong hyperinsulinemia." (PMID 40228209, 2025). "INSR gene polymorphisms are frequently seen among polycystic ovary syndrome patients who also have insulin resistance." (PMID 40105555, 2025). "Insulin resistance then triggers inflammation, oxidative stress, insulin receptor mutations, endoplasmic reticulum stress, and mitochondrial dysfunction." (PMID 40610956, 2025). "ICV administration of low doses of STZ, by changing insulin receptor tyrosine kinase activity and disrupting insulin receptor signaling, causes insulin resistance in the brain, followed by a decrease in glucose and energy metabolism." (PMID 39980585, 2025). "The principal mechanisms of inflammation associated with the development of insulin resistance (IR) encompass a range of inflammatory factors that markedly disrupt the signaling pathways of the insulin receptor." (PMID 40283443, 2025). "Based on our data, we assumed that decreased INSR protein levels in the liver were associated with the development of insulin resistance." (PMID 39747658, 2025). "For insulin receptor (INSR), genetic mutations impair receptor function, disrupting insulin signaling and promoting insulin resistance, a key driver of NAFLD pathogenesis." (PMID 40600138, 2025). "This study identifies the E3 ubiquitin ligase TRIM32 as a critical factor in the degradation of the INSR, leading to a reduction of membrane-associated INSR protein levels and insulin resistance." (PMID 39747658, 2025). "Variants in the INSR gene can impair normal insulin receptor function and result in insulin resistance of varying severity." (PMID 39659391, 2024). "Elevated serum levels of phenylalanine in individuals with T2DM have been linked to alterations in insulin receptor function, contributing to insulin resistance and the onset of T2DM symptoms." (PMID 39593801, 2024). "MFGE8 binds the αvβ5 integrin, increasing the association of αvβ5 with the insulin receptor and resulting in insulin resistance through reduced phosphorylation/activation of the insulin receptor signaling pathway." (PMID 38199575, 2024). "Heterozygous insulin receptor mutations (INSR) are associated with insulin resistance, hyperglycaemia and hyperinsulinaemic hypoglycaemia in addition to hyperandrogenism and oligomenorrhoea in women." (PMID 38461278, 2024). "Evidence suggests that both the expression level and function of the insulin receptor are closely linked to insulin resistance." (PMID 38449844, 2024). "SIT treatment was associated with increased expression of insulin receptor one and decreased expression of makers for insulin resistance, including phospho-PKC- alpha, RBP-4, SIRT1, and PI3K (p<0.05)." (PMID 39074126, 2024). "In severe COVID-19, the ‘negative regulation of the insulin receptor pathway, inferred as a possible cause of IL-6 signalling and inflammatory responses, can lead to ‘insulin resistance’ and ‘increasing blood glucose level’." (PMID 38778394, 2024).